ELAC2 (elaC ribonuclease Z 2)
Description:
Zinc phosphodiesterase, which displays mitochondrial tRNA 3'-processing endonuclease activity. Involved in tRNA maturation, by removing a 3'-trailer from precursor tRNA. Associates with mitochondrial DNA complexes at the nucleoids to initiate RNA processing and ribosome assembly.
Synonyms: HPC2; FLJ10530; COXPD17; ELC2
Tractability: Small molecule: a structure with a bound ligand is known. PROTAC: ubiquitination databases record sites on it; its protein half-life has been measured.
Gene: Protein-coding gene on chromosome 17 (12,991,268 to 13,018,065, reverse strand). Ensembl gene ENSG00000006744.
Subcellular location: Mitochondrion; Mitochondrion matrix, mitochondrion nucleoid; Nucleus
Subcellular location (Human Protein Atlas): Nucleoplasm
Pathways (Reactome):
Metabolism of RNA: rRNA processing in the mitochondrion; tRNA processing in the mitochondrion; tRNA processing in the nucleus
Gene expression (Transcription): tRNA-derived small RNA (tsRNA or tRNA-related fragment, tRF) biogenesis
Gene Ontology:
Molecular function: RNA binding; tRNA-specific ribonuclease activity; RNA endonuclease activity; 3'-tRNA processing endoribonuclease activity
Biological process: mitochondrial tRNA 3'-end processing; tRNA 3'-end processing; mitochondrial tRNA processing; tRNA decay; tRNA processing
Cellular component: endoribonuclease complex; mitochondrial matrix; mitochondrial nucleoid; mitochondrion; nucleoplasm; nucleus; cytosol
Genetic constraint (gnomAD): Loss-of-function variants: 93 observed, 108.29 expected, observed/expected ratio (o/e) 0.86, 90% interval 0.73 to 1.02. The upper end of that interval is the gene's LOEUF score, 1.02, which puts it in group 4 of 6, group 1 being the genes least tolerant of losing a copy. Missense variants: 1,099 observed, 1,092.2 expected, observed/expected ratio (o/e) 1.01, 90% interval 0.96 to 1.06. Synonymous variants: 468 observed, 412.81 expected, observed/expected ratio (o/e) 1.13, 90% interval 1.05 to 1.22.
Gene-disease validity (ClinGen):
ClinGen rates the evidence that ELAC2 causes each of these diseases.
mitochondrial disease (autosomal recessive): Definitive.
Homologues: Orthologues: chimpanzee ELAC2 (99% identical), macaque ELAC2 (94% identical), mouse Elac2 (82% identical), rat Elac2 (82% identical), guinea pig ELAC2 (82% identical), dog ELAC2 (77% identical), pig ELAC2 (77% identical), tropical clawed frog elac2 (61% identical), zebrafish elac2 (57% identical), Drosophila melanogaster RNaseZ (34% identical). Paralogues in human: ELAC1 (11% identical).
Diseases named in the same sentence as ELAC2 in open-access papers:
ELAC2 is named in the same sentence as 58 diseases in open-access papers, as found by Europe PMC text mining. Sharing a sentence is not in itself a finding about the gene and the disease. The quoted sentences say what the papers report.
prostate carcinoma (43 papers, 2002 to 2025). A carcinoma that arises from epithelial cells of the prostate gland. "Mutations in ELAC2 are associated with prostate cancer and are known to cause hypertrophic cardiomyopathy 15–22." (PMID 38826313, 2024). "Mutations in ELAC2 are linked to prostate cancer and are known to cause hypertrophic cardiomyopathy 15–22." (PMID 38826313, 2024). "Many mutations have been identified in ELAC2 related to prostate cancer, some suspected to cause loss of function, but the main mutations are missense changes." (PMID 37093546, 2023). "To functionally investigate the contribution of ELAC2 mutations to the risk of prostate cancer, we developed four in vivo mouse models and investigated their molecular and physiological characteristics." (PMID 37093546, 2023). "These underlying molecular drivers of prostate tumorigenesis in the Elac2 mutant mice provide functional evidence that ELAC2 mutations can predispose to prostate cancer." (PMID 37093546, 2023). "Our physiologically relevant models show that the ELAC2 variant is a predisposing factor for prostate cancer and identify changes that underlie the pathogenesis of this cancer." (PMID 37093546, 2023). "ElaC ribonuclease Z 2 (ELAC2) is primarily associated with prostate cancer, and MARCH6, along with ACSM2B, DEF8, DIS3L, and KCNA5 gene variants, have not been associated with colonic adenomas yet." (PMID 36765865, 2023). "ELAC2 was the first identified prostate cancer susceptibility gene and encodes an RNase Z enzyme, which belongs to the metallo‐β‐lactamase superfamily of proteins found to process the 3′ ends of tRNAs." (PMID 37093546, 2023). "It would be of significant interest to revisit GWAS cohorts to identify secondary oncogenic mutations in patients with ELAC2 variants to identify potential epistatic regulators of prostate cancer." (PMID 37093546, 2023). "A limited role in developing hereditary prostate cancer was attributed to zinc phosphodiesterase ELAC protein 2/histone promoter control protein 2 (ELAC2/HPC2) gene mutations." (PMID 37021836, 2023). "The Elac2 variant or knockout mice on the background of the transgenic adenocarcinoma of the mouse prostate (TRAMP) model show that Elac2 mutation with a secondary genetic insult exacerbated the onset and progression of prostate cancer." (PMID 37093546, 2023). "The most common missense mutations in ELAC2 associated with prostate cancer predisposition are Ser217Leu and Ala541Thr substitutions." (PMID 37093546, 2023). "The generation of tRF-1001 relied on a prostate cancer susceptibility gene, tRNA 3’-endonuclease ELAC2, indicating its specific biological role in prostate cancer." (PMID 36782290, 2023). "Our preliminary study found no direct association between the Ser217Leu and Ala541Thr variants of the HPC2/ELAC2 locus and prostate cancer risk." (PMID 36643816, 2022). "In humans, mutations in ELAC2 are associated with hypertrophic cardiomyopathy and prostate cancer while in C. elegans, loss of HOE-1 has been shown to compromise fertility." (PMID 35451962, 2022). "The main limitation of our study was the small sample size, not allowing us to conclude on the exact role of the Ser217Leu and Ala541Thr variants of the ELAC2 gene in prostate cancer susceptibility." (PMID 36643816, 2022). "In humans, mutations in the ortholog of HOE-1, ELAC2, are associated with both hypertrophic cardiomyopathy and prostate cancer." (PMID 35451962, 2022). "For example, the results of the study offered genetic proof that the prostate carcinoma susceptibility gene ElaC ribonuclease Z 2 (ELAC2) perhaps participated in RNA processing, particularly rRNA processing and mitochondrial function." (PMID 36262249, 2022). "The objective of the present study was to analyze the carriage of the C650T (Ser217Leu) and G1621A (Ala541Thr) mutations of the ELAC2 gene and the risk factors in prostate cancer patients in Burkina Faso." (PMID 36643816, 2022).
prostate carcinoma (continued). "It is with this in mind that this preliminary study was conducted to determine the involvement of the Ser217Leu (C650T) and Ala541Thr (G1621A) variants of the ELAC2 gene in prostate cancer in the Burkinabe population." (PMID 36643816, 2022). "For example, the R781H substitution in RNase ZL/ELAC2, which has been linked with prostate cancer and hypertrophic cardiomyopathy, mainly affects mt-tRNA processing while has no major differences on the nuclear pre-tRNA processing." (PMID 34539450, 2021). "tRF-1001 is present in the cytoplasm and is produced by tRNA 3′-endonuclease ELAC2 (a prostate cancer susceptibility gene), and it is required for the proliferation of prostate cancer cells." (PMID 32887641, 2020). "Mutations of the ELAC2 gene have been found to confer increased prostate cancer susceptibility in families." (PMID 31452838, 2019). "ELAC2 is of particular interest in prostate cancer because sequence variants of this gene have been suggested to play a role in genetic susceptibility to hereditary and sporadic forms of the disease." (PMID 31452838, 2019). "The study described herein was undertaken to determine the prevalence and association of the Ser217Leu variant of the ELAC2 gene in prostate cancer patients of the Littoral Region of Cameroon." (PMID 31321101, 2019). "Other studies also found that the genotype of ELAC2 is associated with a high risk of sporadic prostate cancer." (PMID 26241669, 2015). "Mutations in ELAC2, a human gene encoding RNase ZL, have been associated with the occurrence of prostate cancer (PCA) and infantile hypertrophic cardiomyopathy (HCM)." (PMID 26553808, 2015). "Six centenarians carried the A541T variant in the gene ELAC2 (rs5030739) that was reported to be associated with prostate cancer." (PMID 25333069, 2014). "The association of one of HPC2/ELAC2 polymorphic variants (Thr541) with prostate cancer seems to be weak." (PMID 24282788, 2013). "Two common missense variations in ELAC2 gene (A541T; OMIM_ID # 605367.0002 and S217L; OMIM_ID # 605367.0001) implicated in genetic susceptibility to heredity prostate cancer were found in the SAIF genome." (PMID 22938532, 2012). "It is important to note that ELAC2 is a candidate prostate cancer susceptibility gene as its mutations are associated with prostate cancer." (PMID 21781332, 2011). "We have undertaken a genetic study of yeast TRZ1 gene, the homolog of prostate cancer susceptibility gene ELAC2." (PMID 15892892, 2005). "The human homolog of TRZ1, ELAC2, was identified as a candidate prostate cancer susceptibility gene." (PMID 15892892, 2005). "Since ELAC2 cannot functionally complement TRZ1 deletion, we cannot directly test in yeast the functional effect of the human ELAC2 missense substitution A541T, which appears to confer modest risk of prostate cancer." (PMID 15892892, 2005). "The Thr541 variant in the HPC2/ELAC2 gene has previously been reported to be at an increased frequency in prostate cancer cases." (PMID 12373607, 2002). "Prostate cancer developed in both models when the mutations were bred on the transgenic adenocarcinoma of mouse prostate (TRAMP) background, implicating ELAC2 mutations as susceptibility factors for prostate cancer in the presence of additional genetic insults." (PMID 38779771, 2024). "We analysed the nuclear and mitochondrial transcriptomes and proteomes, miRNAs and small RNAs to show that reduced ELAC2 levels and activity predispose to prostate cancer by impairing the function of noncoding RNAs such as tRNAs, lncRNAs and miRNAs, which in turn alter immunometabolism." (PMID 37093546, 2023). "Yet another study conducted in 2015 on the whole genome sequencing of the Pashtun population in the northwest showed that a single nucleotide variation representing Ser217Leu in the ELAC2 gene (rs4792311) was also found and was implicated in genetic susceptibility to hereditary prostate cancer." (PMID 37710250, 2023).
prostate carcinoma (continued). "We investigated and graded the prostate lobes of the KO‐TRAMP and A537T‐TRAMP compared with the WT‐TRAMP mice to determine whether mutation of Elac2 can potentiate or exacerbate prostate cancer." (PMID 37093546, 2023). "A larger study is needed to better understand the role of different SNPs of ELAC2, other risk factors, and other genes in prostate cancer predisposition, which may benefit early diagnosis of the disease in at-risk individuals and management of the disease." (PMID 36643816, 2022). "Enzymes that are targeted into mitochondria could affect mt-tRF biogenesis, like RNase ZL/ELAC2, which has been identified as a hotspot for mutations linked with mitochondrial diseases, such as hypertrophic cardiomyopathy but also with prostate cancer." (PMID 34539450, 2021). "This metaanalysis showed that Ser217Leu and Ala541Thr polymorphism of ELAC2 gene is accompanied by increase of risk of prostate cancer and may be the markers which are sensitive to low penetration of the prostate cancer." (PMID 32592348, 2020). "Results of this research showed that, in the individuals with the prostate cancer, there is a relationship between Ser217Leu and Ala541Thr polymorphism of ELAC2 gene and/with prostate cancer, and the suspicious individuals gotten involved in the mutation must take action to prevent this cancer." (PMID 32592348, 2020). "Topical simulation and screening of the mutations introduced a gene named HPC2/ELAC2 as suppressor of prostate cancer which this gene possesses the hazardous mutations related to relational prostate cancer ELAC2 protein is an enzyme on phosphodiesterase encoded by ELAC2 gene in human." (PMID 32592348, 2020). "The association between the c.2342 G>A (p.Arg781His) ELAC2 variant and prostate cancer as a consequence of impaired mitochondrial RNase Z activity could indicate a functional link between tumorigenesis and mitochondrial RNA metabolism." (PMID 31045291, 2019). "Our results provide genetic evidence that prostate cancer susceptibility gene ELAC2 may be involved in RNA processing, especially rRNA processing and mitochondrial function." (PMID 15892892, 2005). "In humans, mutation of ELAC2 is associated with an increased risk of prostate cancer." (PMID 15892892, 2005). "At present the role that sequence variants in ELAC2 may play in the genesis of prostate cancer is unclear." (PMID 15892892, 2005). "Earlier work suggested that loss of ELAC2 might drive prostate cancer aggressiveness." (PMID 31452838, 2019). "Interestingly, different GWAS have reported contrasting findings about the predisposing impact of the ELAC2 A541T variant to prostate cancer, although none of the studies considered the presence of secondary somatic mutations that may be necessary for prostate tumorigenesis." (PMID 37093546, 2023). "ELAC2 is also responsible for generating cytoplasmic tRF1 which is derived from pre-tRNA-Ser in prostate cancer cells." (PMID 33604354, 2020). "ELAC1 appears to correspond to the C-terminal half of 3′tRNase from ELAC2 and it was found that ELAC1 also has 3′-tRNase activity, possibly encoding a candidate prostate cancer susceptibility gene for tRNA 3′ processing endoribonucleases." (PMID 31998783, 2020). "The tRF-1s were found to be cleaved by ELAC2 in the cytoplasm, and tRF-1 expression levels are regulated by ELAC2 in prostate cancer cell lines." (PMID 33041815, 2020). "Camp and Tavtigation, (2002) carried out a meta-analysis for the data related to relationship of Ser217Leu and Ala541Thr alleles in the ELAC2 (HPC2) gene and prostate cancer." (PMID 32592348, 2020). "This reaction requires zinc ions as cofactors of reaction From clinical viewpoint, variables of the ELAC2 gene are related to hereditary prostate cancer." (PMID 32592348, 2020). "Nuclear ELAC2 staining was seen in 5,634 of 9,262 (60.8%) prostate cancers and was considered weak in 26.3%, moderate in 26.6% and strong in 7.9%." (PMID 31452838, 2019).
prostate carcinoma (continued). "The link between ELAC2 up-regulation and prostate cancer phenotype suggests a possible functional role of ELAC2 for the biology of the disease." (PMID 31452838, 2019). "Only one published study has evaluated ELAC2 protein expression by immunohistochemistry in prostate cancer." (PMID 31452838, 2019). "The results of the present study identify nuclear ELAC2 expression as a weak to moderate prognostic feature in prostate cancers." (PMID 31452838, 2019). "In summary, nuclear ELAC2 overexpression is a frequent feature in prostate cancer with a potential role for tumor development and progression." (PMID 31452838, 2019). "High-level nuclear ELAC2 staining was associated with TMPRSS2:ERG rearrangement and ERG expression in prostate cancers (p< 0.0001 each)." (PMID 31452838, 2019). "To date, germline mutations have been found in three candidate genes for hereditary prostate cancer: ELAC2 at 17p11, RNASEL at 1q25 and MSR1 at 8p22." (PMID 15714208, 2005). "To date, three strong candidates are known, RNASEL at 1q25, ELAC2 at 17p11 and MSR1 at 8p22, each having been identified with germline mutations in prostate cancer families." (PMID 15714208, 2005). "Unlike E. coli RNase Z, ELAC2 is essential in humans and is linked to increased prostate cancer susceptibility." (PMID 41264253, 2025). "The Ala541Thr variant led to reduced ELAC2 activity that resulted in impaired mitochondrial and nuclear tRNA processing and validated the role of ELAC2, causing prostate hyperplasia and inflammation with age, but not prostate cancer." (PMID 38779771, 2024). "The ELAC2 gene was identified as a prostate cancer susceptibility gene more than two decades ago, but its mechanistic and physiological roles in prostate cancer development had not been explored until this work." (PMID 37093546, 2023). "Polymorphisms in ELAC2 have been correlated with prostate cancer, but a definitive link has been lacking." (PMID 37093546, 2023). "We did not detect an association between prostate cancer risk and the Ser217Leu (p=0.972) and Ala541Thr (p=0.267) variants of the ELAC2 gene." (PMID 36643816, 2022). "Variables of ELAC2 gene are accompanied by hereditary prostate cancer." (PMID 32592348, 2020). "ELAC2 staining was predominantly localized in the nucleus of invasive prostate cancer cells." (PMID 31452838, 2019). "The IHC analysis showed nuclear ELAC2 staining in 60.8% of the prostate cancers." (PMID 31452838, 2019). "Nuclear ELAC2 staining was observed in 60.8% of prostate cancers." (PMID 31452838, 2019). "The Tobago Prostate Cancer Screening Study has also investigated several metabolic and genetic aspects of prostate cancer including the role of human herpes virus 8, chemoprevention with lycopene and the role of genetic influences such as the ELAC2 and RANSEL genes." (PMID 29743948, 2018). "Although rare variants of other genes such as RNASEL, MSR1, and ELAC2 have been previously identified in prostate cancer families and proposed as prostate cancer susceptibility alleles, follow-up studies have not supported their candidacy." (PMID 23064873, 2013). "Furthermore, several genes implicated as hereditary prostate cancer tumor suppressor genes such as HPC/ELAC2 and RNASEL have been linked to increased risk of prostate cancer in African Americans." (PMID 21603658, 2011). "Recent demonstrations that hoe-1, the C. elegans homolog of ELAC2, plays a role in germline proliferation, and human ELAC2 maybe involved in cell cycle regulation, may help better illuminate the contribution of ELAC2 to the etiology of human prostate cancer." (PMID 15892892, 2005). "The higher level of nuclear ELAC2 staining in cancers (35% with moderate to strong staining) as compared to normal prostate epithelial tissue (typically negative or only weakly positive) suggests that nuclear ELAC2 becomes up-regulated during malignant transformation in a subset of prostate cancers." (PMID 31452838, 2019).
prostate carcinoma (continued). "In summary, our investigation supports a role for BRCA2 and HOXB13 mutations in prostate cancer predisposition and provides reassurance that BRCA1, RNASEL, and ELAC2 are not substantially contributory in this cohort." (PMID 40433050, 2025). "For prostate cancer, we analyzed 5 genes and did not observe an over-representation of SNP associations at p<0.05 (observed/tested: BRCA2, 2/83; ELAC2, 1/9, HOXB13, 0/2; MSR1, 1/22; RNASEL, 2/21)." (PMID 23555315, 2013). "However, studies assessing the expression profile and putative prognostic role of the ELAC2 protein in prostate cancer are lacking." (PMID 31452838, 2019). "We confirm alterations in six genes previously associated with prostate cancer (MAP3K7, MELK, RCBTB2, ELAC2, TPD52, ZBTB4), and also identify 94 genes not previously linked to prostate cancer progression that would not have been detected using either transcript or copy number data alone." (PMID 26501111, 2015).